SNORA66 (small nucleolar RNA, H/ACA box 66)
Synonyms: U66; RNU66
Gene: Small nucleolar RNA gene on chromosome 1 (92,840,719 to 92,840,851, forward strand). Ensembl gene ENSG00000207523.
Gene Ontology:
Biological process: RNA processing
Cellular component: nucleolus
Homologues: Orthologues: chimpanzee SNORA66 (99% identical), macaque SNORA66 (96% identical), rabbit SNORA66 (89% identical), guinea pig SNORA66 (87% identical), rabbit SNORA66 (86% identical), dog SNORA66 (85% identical), rat SNORA66 (83% identical), pig SNORA66 (83% identical), mouse Gm26387 (80% identical), tropical clawed frog SNORA66 (60% identical), tropical clawed frog SNORA66 (59% identical).
Diseases named in the same sentence as SNORA66 in open-access papers:
SNORA66 is named in the same sentence as 3 diseases in open-access papers, as found by Europe PMC text mining. Sharing a sentence is not in itself a finding about the gene and the disease. The quoted sentences say what the papers report.
diffuse large B-cell lymphoma (1 paper, 2025). "For instance, Li and colleagues found upregulated expression of SNORA66 in human patients with diffuse large B-cell lymphomas." (PMID 40936092, 2025).
SNORA66 also shares sentences with these, for which no sentence is quoted: infection (1 paper); mastitis (1).